CSTF2 (cleavage stimulation factor subunit 2)
Diseases named in the same sentence as CSTF2 in open-access papers (continued):
Sharing a sentence is not in itself a finding about the gene and the disease.
tumor (14 papers, 2017 to 2025). "By using mouse subcutaneous xenograft models, we also found that CSTF2 overexpression significantly enhanced but silence markedly suppressed the growth rates of PDAC tumor." (PMID 37816727, 2023). "To further verify the tumor-promoting function of CSTF2, we overexpressed CSTF2 in the HCC cell line Hep3B and confirmed that the expression level of CSTF2 was higher than that of vector control by Western blot." (PMID 35875122, 2022). "Following experiments revealed that CSTF2 knockdown-induced tumor repressing effects or CSTF2 overexpression-induced tumor promoting effects were reversed by 740Y-P treatment or Wortamnnin, respectively." (PMID 35412944, 2022). "Further experiments validated that 740Y-P treatment reversed CSTF2 knockdown-triggered tumor-repressing effects on HCCLM3 cells." (PMID 35412944, 2022). "Similarly, Wortmannin treatment also abolished CSTF2 overexpression-induced tumor promoting effects on Huh7 cells." (PMID 35412944, 2022). "Furthermore, the tissue microarray analysis of 48 pairs of HCC tissues also showed that CSTF2 was more strongly expressed in tumor tissues than in adjacent non-tumor tissues." (PMID 35875122, 2022). "Moreover, the tumorigenic function of CSTF2 in vivo was measured by a subcutaneous tumor formation or injecting four plasmids into a mouse tail vein within 5–7 s in an immunocompetent HCC mouse model." (PMID 35875122, 2022). "Moreover, the HCC tissue microarray confirmed that the expression of CSTF2 in tumor tissues is much higher than that in adjacent non-tumor normal tissues from different HCC patients." (PMID 35875122, 2022). "After tumor mutation profile and copy number variation (CNV) analyses, we established and validated a prediction model of KRAS mutations, based on survival analysis and mRNA expression, that contained seven genes: CSTF2, FAF2, KIF20B, AKR1A1, APOM, KRT6C, and CD70." (PMID 38268915, 2023). "This indicated that the mechanism of CSTF2 in regulating tumor in vivo may be more complex." (PMID 35370655, 2022). "The results showed that CSTF2 could affect DNA repair and methylation in tumor cells." (PMID 35370655, 2022). "In our study, although the mutation of CSTF2 did not directly affect the prognosis of tumor patients, we speculated that the gene may play an important regulatory role by affecting other important activities in cells." (PMID 35370655, 2022). "However, the tumor-promoting function and molecular mechanism of CSTF2 in HCC remain unclear." (PMID 35875122, 2022). "We first performed subcutaneous tumor formation experiments by injecting 1×106 cells into the right back of BALB/c nude mice in the vector control group and CSTF2 sgRNA group, respectively." (PMID 35875122, 2022). "In terms of the molecular mechanism of CSTF2 on HCC, GO and KEGG enrichment analyses revealed that the high expression of CSTF2 is related to the cell cycle and DNA replication, which contribute to tumor proliferation." (PMID 35875122, 2022).
neurodevelopmental disorder (1 paper, 2024). A behavioral and cognitive disorder with onset during the developmental period that involves impaired or aberrant development of intellectual, motor, or social functions. "Among these, only PCDH19 and SRPX2 have been demonstrated to cause neurodevelopmental disorder and/or seizures, while a missense variant in CSTF2 gene has been proposed to cause mild speech delay and learning difficulties in affected males." (PMID 39457436, 2024). "This duplication contains 17 genes, of which only the PCDH19 and SRPX2 genes have been related to neurodevelopmental disorders, while for the CSTF2 gene, this relationship is provisional." (PMID 39457436, 2024).
CSTF2 also shares sentences with these, for which no sentence is quoted: lung adenocarcinoma (3 papers); colon adenocarcinoma (2); melanoma (2); connective tissue disorder (1); endometrial carcinoma (1); glioma (1); head and neck cancer (1); heart failure (1); Infertility (1); kidney cancer (1); male infertility (1); metastatic colorectal cancer (1); oral squamous cell carcinoma (1); uterine corpus endometrioid carcinoma (1).